ADORA3 (adenosine A3 receptor)
Description:
G protein-coupled receptor (GPCR) for adenosine that plays significant roles in various physiological processes including immune regulation, cardioprotection and neuroprotection. Also acts as a receptor for adenosines containing N(6)-methylated adenine (m6A) post-transcriptional modification, which are derived from the degradation of RNAs (mRNAs, rRNAs and tRNAs): activated by N(6)-methyladenosine (m6A), N(6),N(6)-dimethyladenosine (m6,6A) and N(6)-isopentenyladenosine (i6A). Preferentially couples to the inhibitory G protein (Gi), leading to the suppression of adenylate cyclase activity and a reduction in intracellular cyclic AMP levels. Upon adenosine binding, mediates cardioprotection in cardiomyocytes through anti-apoptotic effects primarily via the ERK1/2 pathway as well as the PI3K pathway. In the central nervous system, participates in the modulation of synaptic plasticity, including long-term potentiation (LTP) and long-term depression (LTD) in the hippocampus (By similarity). In lung mast cells, receptor activation contributes to the type I allergic response by facilitating mast cell degranulation and histamine release (By similarity). Highly expressed in inflammatory cells such as neutrophils and mast cells, inhibits neutrophil degranulation and reduces superoxide production, thereby modulating inflammatory responses. [Isoform 2]: Receptor for adenosine. The activity of this receptor is mediated by G proteins which inhibits adenylyl cyclase.
Synonyms: AD026; A3AR
Tractability: Small molecule: an approved drug acts on it; a structure with a bound ligand is known; a high-quality ligand is known; it belongs to a druggable protein family. Antibody: its Gene Ontology location is reachable by antibodies, with high confidence; UniProt places it where antibodies can reach, with medium confidence; UniProt predicts a signal peptide or a membrane-spanning region. PROTAC: a small molecule that binds it is known.
Target class: Family A G protein-coupled receptor; Membrane receptor; Small molecule receptor (family A GPCR); Adenosine receptor; Nucleotide-like receptor (family A GPCR)
Chemical probes: KINETIN RIBOSIDE, PD082085, PD134520, PD134521
Safety:
Unwanted effects reported when the protein is acted on. In parentheses: how it was acted on, where the effect was seen, and who reports it.
angiogenesis (activation; cardiovascular system, immune; source: Urban et al. (2012))
antiischaemic (cardioprotective) (activation; cardiovascular system, immune; source: Urban et al. (2012))
cell necrosis (activation; cardiovascular system, immune; source: Urban et al. (2012))
cell proliferation (activation; cardiovascular system, immune; source: Urban et al. (2012))
decreased convulsions (activation, acute dosing; nervous system, respiratory; source: Lynch et al. (2017))
decreased locomotor activity (activation, acute dosing; nervous system, respiratory; source: Lynch et al. (2017))
decreased pain (activation, acute dosing; nervous system, respiratory; source: Lynch et al. (2017))
hypertension (inferred by author) (inhibition; cardiovascular system, immune; source: Urban et al. (2012))
hypotension (activation; cardiovascular system, immune; source: Urban et al. (2012))
immunosuppression (activation; cardiovascular system, immune; source: Urban et al. (2012))
increased bronchoconstriction (activation, acute dosing; nervous system, respiratory; source: Lynch et al. (2017))
increased convulsions (inhibition, acute dosing; nervous system, respiratory; source: Lynch et al. (2017))
interference with the regulation of cell growth (inferred by author) (inhibition; cardiovascular system, immune; source: Urban et al. (2012))
myocardial ischemia (inferred by author) (inhibition; cardiovascular system, immune; source: Urban et al. (2012))
proinflammatory effects (inferred by author) (inhibition; cardiovascular system, immune; source: Urban et al. (2012))
proischemic (cerebral) (activation; cardiovascular system, immune; source: Urban et al. (2012))
Gene: Protein-coding gene on chromosome 1 (111,499,429 to 111,503,633, reverse strand). Ensembl gene ENSG00000282608.
Subcellular location: Cell membrane
Pathways (Reactome):
Signal Transduction: Adenosine P1 receptors; G alpha (i) signalling events
Gene Ontology:
Molecular function: G protein-coupled adenosine receptor activity; G protein-coupled receptor activity
Biological process: adenylate cyclase-inhibiting G protein-coupled receptor signaling pathway; negative regulation of cell migration; negative regulation of cell population proliferation; activation of adenylate cyclase activity; G protein-coupled adenosine receptor signaling pathway; inflammatory response; positive regulation of mast cell degranulation; regulation of heart contraction; response to wounding; signal transduction; G protein-coupled receptor signaling pathway; presynaptic modulation of chemical synaptic transmission; regulation of norepinephrine secretion
Cellular component: dendrite; plasma membrane; synapse; membrane; presynaptic membrane; Schaffer collateral - CA1 synapse
Genetic constraint (gnomAD): Loss-of-function variants: 4 observed, 7.58 expected, observed/expected ratio (o/e) 0.53, 90% interval 0.26 to 1.2. That is too few expected variants to judge how well the gene tolerates losing a copy. Missense variants: 343 observed, 410.59 expected, observed/expected ratio (o/e) 0.84, 90% interval 0.76 to 0.91. Synonymous variants: 168 observed, 160.94 expected, observed/expected ratio (o/e) 1.04, 90% interval 0.92 to 1.19.
Homologues: Orthologues: dog ADORA3 (87% identical), rabbit ADORA3 (75% identical), guinea pig ADORA3 (75% identical), rat Adora3 (74% identical), mouse Adora3 (74% identical), tropical clawed frog XB1010847 (53% identical), tropical clawed frog adora3.2 (51% identical), tropical clawed frog adora3.1 (47% identical), zebrafish adora3a.1 (38% identical), Drosophila melanogaster AdoR (33% identical). Paralogues in human: ADORA1 (49% identical), ADORA2A (40% identical), ADORA2B (39% identical).
Diseases named in the same sentence as ADORA3 in open-access papers:
ADORA3 is named in the same sentence as 121 diseases in open-access papers, as found by Europe PMC text mining. Sharing a sentence is not in itself a finding about the gene and the disease. The quoted sentences say what the papers report.
melanoma (14 papers, 2011 to 2025). A malignant, usually aggressive tumor composed of atypical, neoplastic melanocytes. "Previous studies have found that ADORA3 is highly expressed in a variety of malignant tumors, including melanoma, breast cancer, prostate cancer, liver cancer, pancreatic cancer, lung cancer, lymphoma, glioblastoma, and malignant pleural mesothelioma." (PMID 40362672, 2025). "The A3 adenosine receptor (ADORA3) is a G-protein coupled cell surface receptor expressed on many immune cells as well as cancer cells including melanoma." (PMID 36291758, 2022). "Downregulated β-catenin in melanoma cells due to the administration of an inflammatory regulator adenosine A3 receptor has demonstrated the role of Wnt/β-catenin in asthma." (PMID 35000533, 2022).
asthma (10 papers, 2015 to 2023). "In applications to ABRIDGE and CAMP cohorts, we find evidence of both differential co-expression and differential expression across ACT scores for ADORA3, ALOX15, and IDO1, all genes which have been previously implicated in asthma." (PMID 37275375, 2023). "Results suggest that both expression levels and covariances of ADORA3, ALOX15, and IDO1 are associated with asthma control." (PMID 37275375, 2023). "The adenosine receptors (ADORA1, ADORA2A, ADORA2B, and ADORA3) have a promising therapeutic role in asthma and chronic obstructive pulmonary disease (COPD)." (PMID 35052792, 2022). "Similarly, using whole blood samples, polymorphisms of ADORA3 have been identified in patients with aspirin-induced urticaria, of ADORA1 and ADORA2A in aspirin-induced asthma, both in Korean population; ADA polymorphism have been observed in asthma patients from a Chinese Han population." (PMID 34068999, 2021). "However, the role of ADORA3 in human airway inflammation is not yet fully understood, thus it is still unclear whether agonists or antagonists of ADORA3 would be of any value for the treatment of asthma and COPD." (PMID 35386996, 2021).
colon carcinoma (10 papers, 2003 to 2024). "The inhibitory effects of cordycepin on colon cancer via various mechanisms have been well documented, including the inhibition of colon cancer cell growth after binding to the adenosine A3 receptor (A3R)." (PMID 39062140, 2024). "There is increasing evidence proving that ADORA3 is overexpressed in several cancers, including breast cancer, thyroid cancer, bladder cancer, and colon cancer and functions as a tumor promoter." (PMID 33441161, 2021).
Arthritis (9 papers, 2006 to 2024). Inflammation of a joint. "Adenosine A3 receptor agonists thus ameliorate joint inflammation in several murine models of arthritis." (PMID 16519795, 2006). "The widely expressed adenosine A3 receptor (A3AR) has been implicated in a range of diseases including immune conditions, and compounds that aim to selectively target this receptor are currently under development for arthritis." (PMID 30919204, 2019). "Interestingly, studies in rat suggest that adenosine A3 receptor agonists can preserve bone mass in adjuvant induced arthritis and prevent bone destruction in osteoarthritis." (PMID 21276240, 2011). "The specific adenosine A3 receptor (A3AR) agonist (CF101) has potential for inflammation and pain in various disease, such as arthritis, cancer and neuropathic pain, while the role of A3AR in post‐traumatic OA and the underlying mechanism is largely unknown." (PMID 35775127, 2022).
hepatocellular carcinoma (9 papers, 2013 to 2026). A malignant tumor that arises from hepatocytes. "Both of LIN and DEG showed inhibitory profile against hepatocellular carcinoma cell lines with induction of apoptosis at G2/M phase with increase in caspase-3 levels, accompanied by a downregulation in gene and protein expression levels of ADORA3 with a subsequent increase in cAMP." (PMID 29768061, 2018).
breast carcinoma (8 papers, 2018 to 2025). "ENTPD1, NT5E, and ADORA3 showed higher expression in bone metastases than in primary breast cancers,top, GSE47561." (PMID 36186774, 2022). "The IHC images obtained from HPA indicated that these seven PRGs (except ADORA3) expressed in human colorectal cancer, breast cancer, prostate cancer, lung cancer, and Non-Hodgkin’s Lymphoma." (PMID 36551263, 2022). "This could be ascribed to their interaction with various breast cancer-associated protein targets such as CAs, AKR1B1, ADORA3, PTPN1, ESR2, and EGFR." (PMID 39482666, 2024). "In primary ER+ breast cancer, high levels of the triplet ENTPD1/NT5E/ADORA3 expression signature was correlated with lower overall, distant metastasis-free, and progression-free survival." (PMID 36186774, 2022). "The ENTPD1/NT5E/ADORA3 expression signature was not correlated with either outcome in ER–, HER2-enriched, or basal breast cancers, which do not share the same metastatic behavior, nor were signatures combining expression of the ectonucleotidases with any of the other aADO receptors in ER+ tumors." (PMID 36186774, 2022).
glioma (8 papers, 2011 to 2024). A benign or malignant brain and spinal cord tumor that arises from glial cells (astrocytes, oligodendrocytes, ependymal cells). "Additionally, FDA-approved drug targets among these genes revealed 30 such targets, with CDK4 and FCGR1A identified as glioma-specific and ADORA3 as brain-specific, according to the Human Protein Atlas." (PMID 39457550, 2024). "Glioblastomas also demonstrate higher levels of multiple adenosine receptors (ADORA1/A1R, ADORA3/A3R) compared to all other cancer subtypes, suggesting that gliomas may have particularly active purinergic signaling, and therefore represent an attractive target for anti-CD73 therapy." (PMID 35973991, 2022).
prostate carcinoma (8 papers, 2012 to 2025). A carcinoma that arises from epithelial cells of the prostate gland. "A 3-gene signature composed of ENTPD1, NT5E, and ADORA3 is associated with a greater chance of bone metastasis in ER+ breast and prostate cancers." (PMID 36186774, 2022). "We showed that expression of a three-gene expression signature comprising ENTPD1, NT5E, and ADORA3 in primary ER+ breast and prostate cancers was correlated with bone metastases." (PMID 36186774, 2022). "We also analyzed gene expression in metastatic prostate cancer (GSE74685) and found a similar expression pattern, with ENTPD1, NT5E, and ADORA3 upregulation in bone metastases than in other metastases, bottom." (PMID 36186774, 2022). "In one study, the activation of ADORA3 with the ADORA3 agonist N6-(3-iodobenzyl) adenosine-5′-n-methylureamine inhibited adenylate cyclase in AT6.1 rat prostate cancer cells and thus inhibited PKA-mediated ERK1/2 activation, leading to a reduction in prostate cancer cell proliferation." (PMID 40362672, 2025).
psoriasis (8 papers, 2013 to 2024). An autoimmune condition characterized by red, well-delineated plaques with silvery scales that are usually on the extensor surfaces and scalp. "In that context, novel orally active drugs for the management of moderate-to-severe psoriasis are under development, including Piclidenoson (CF101), an adenosine A3 receptor (A3R) agonist." (PMID 35572558, 2022).
glioblastoma (7 papers, 2016 to 2025). The most malignant astrocytic tumor (WHO grade IV). "Analysis of adenosine receptors showed that expression of ADORA2A/A2AR and ADORA2B/A2BR in glioblastoma and diffuse glioma were moderate compared to that of other cancers, while ADORA1/A1R and ADORA3/A3R were expressed at significantly higher levels in glioblastoma compared to all other tumor types." (PMID 35973991, 2022). "ADORA3 is a sensor for adenosine that is released by glioblastoma cell ectonucleotidases." (PMID 32299465, 2020).
lung carcinoma (7 papers, 2011 to 2025).
Cerebral ischemia (6 papers, 2022 to 2025). Restriction of arterial blood supply to the brain associated with insufficient oxygenation to support the metabolic requirements of the tissue. "ADORA3 has been found to alleviate dysfunction caused by cerebral ischemia and brain injury; however, its effect on ICH has not been explored." (PMID 38977622, 2025). "Following the identification of ADORA3 through protein–protein interaction analysis and the application of the clustering coefficient and eccentricity algorithms, our focus shifted to investigating the alterations in adenosine and ADORA3 following cerebral ischemia and hypoxia." (PMID 38715283, 2024). "Furthermore, in an in vitro model simulating cerebral ischemia through hypoxia and glucose deprivation (OGD), ADORA3 antagonists prevented injury‐induced synaptic failure and excitotoxic damage." (PMID 38715283, 2024).
diabetes (6 papers, 2013 to 2022). "The adenosine A2A receptor mRNA and protein levels are increased in the renal cortex of diabetic rats, and diabetes has also been associated with increased glomerular expression of adenosine A2B receptors and increased cortical levels of the adenosine A3 receptor protein." (PMID 31150459, 2019). "Our first approach was to evaluate the physiological effects of the ADORA3 antagonists administered to rats following one month from induction of experimental diabetes for a period of four weeks." (PMID 31540220, 2019). "The use of the ADORA3 antagonists MRS1220 or MRS1523 blocked the diabetes-inducing effect on this form of the protease." (PMID 31540220, 2019). "Unlike what happened when treating diabetic rats with ADA, ADORA3 antagonism does not significantly affect the levels of IL-10, while only attenuates the levels of IL-6 found in diabetes." (PMID 31540220, 2019). "Differently, in SHR, induction of diabetes with STZ did not alter the expression of the membrane-bound adenosine A3 receptor, suggesting that the modulatory role of adenosine on its receptors might also depend on the health condition of the animal (diabetic vs. hypertensive-diabetic)." (PMID 33238361, 2020). "Interestingly, in normotensive animals, STZ-induced diabetes increased renal adenosine levels and did not alter adenosine A3 receptor mRNA in the kidney, although it increased membrane-associated A3 protein levels in the renal cortex and decreased it in the renal medulla." (PMID 33238361, 2020).
glaucoma (6 papers, 2006 to 2022). Increased pressure in the eyeball due to obstruction of the outflow of aqueous humor. "Previously, we demonstrated that the activation of adenosine A3 receptor (A3R) affords protection to the retina, including RGCs, unveiling the possibility for a new strategy for glaucoma treatment." (PMID 33007835, 2020).
ischemia (6 papers, 2012 to 2024). A hypoperfusion of the BLOOD through an organ or tissue caused by a PATHOLOGIC CONSTRICTION or obstruction of its BLOOD VESSELS, or an absence of BLOOD CIRCULATION. "The signaling of ADORA3 protects cardiomyocytes against the damage of ischemia, as well as protects it from energy depletion and contractile dysfunction." (PMID 36056346, 2022). "Moreover, ADORA3 expression was notably elevated in microglia within the white matter in mice after BCAS, indicating that ADORA3 likely modulates the function of microglia in chronic ischemia‐induced WMI." (PMID 38715283, 2024). "The adenosine-A3 receptor (A3AR) belongs to a family of four GPCRs (A1, A2A, A2B, and A3) that respond to adenosine and are attractive drug targets for a number of pathophysiologic conditions including cancer, ischemia, cardiovascular disease, and inflammation." (PMID 22999879, 2012).
Stroke (6 papers, 2019 to 2025). Sudden impairment of blood flow to a part of the brain due to occlusion or rupture of an artery to the brain. "HU-010 targeting ADORA3 is undergoing a phase III clinical trial in the treatment of stroke as an indication." (PMID 38977622, 2025). "Early study in gerbils injected with ADORA3 agonists after stroke showed impairment of postischemic blood flow, extensive hippocampal neuronal destruction, and increased mortality, suggesting that the activation of ADORA3 played a harmful role in the process of acute ischemic injury." (PMID 38715283, 2024).
colitis (5 papers, 2014 to 2020). Inflammation of the colon. "The role of the adenosine A3 receptor (A3AR) in experimental colitis is controversial." (PMID 25762375, 2015).